CSF1 (colony stimulating factor 1)
Diseases named in the same sentence as CSF1 in open-access papers (continued):
Sharing a sentence is not in itself a finding about the gene and the disease.
rheumatoid arthritis (25 papers, 2010 to 2024). A chronic, systemic autoimmune disorder characterized by inflammation in the synovial membranes and articular surfaces. "Serum IL-34 and CSF1 are linked to the disease activity in patients with rheumatoid arthritis and osteoporosis." (PMID 32801364, 2020). "Pigmented villonodular synovitis (PVNS) is a rare inflammatory articular disease sharing common characteristics with rheumatoid arthritis (RA), notably hyperplasia of the synovium due to a hyperproliferation of synoviocytes, and with cancer owing to mutations of the CSF1/M-CCSF gene." (PMID 35264617, 2022). "CSF1 is involved in the pathogenesis of different chronic inflammatory diseases including rheumatoid arthritis (RA) and systemic lupus erythematosus." (PMID 35675127, 2022). "In rheumatoid arthritis, CCR5 increased expression has also been related with higher levels of CSF-1 and IL-1029." (PMID 28273887, 2017). "A FPA008 trial in 12 rheumatoid arthritis patients and a phase 1 study of ARRY-382 in cancer patients have been reported as meeting abstracts and show that CSF1R inhibition leads to increased serum CSF1 and/or IL-34 levels and diminished NTX228,229." (PMID 32801364, 2020).
tenosynovial giant cell tumor (24 papers, 2010 to 2025). A tumor usually arising in the synovium of joints, bursa or tendon sheath. "Additionally, translocation of the CSF-1 gene has been shown to result in the hyperexpression of macrophage CSF-1, which is implicated in the development of tenosynovial giant cell tumor (TGCT)." (PMID 36980578, 2023). "So far, the FDA has approved two CSF-1R inhibitors for patients with tenosynovial giant cell tumors, a tumor type characterized by chromosomal translocations of the CSF-1 gene, leading to aberrant CSF-1 expression." (PMID 40646332, 2025). "So far, one CSF1R inhibitor (pexidartinib) has obtained FDA approval but only in the setting of tenosynovial giant cell tumors, a tumor type that aberrantly expresses CSF1 in neoplastic cells due to chromosomal translocations involving the CSF1 gene." (PMID 37505292, 2023). "Our studies were inspired by the findings of CSF1 rearrangement and its overexpression in tenosynovial giant cell tumors (TSGCT), attracting dendritic cells including Langerhans cells (CSF1 receptor+) to migrate into the mesenchymal tumor and proliferate." (PMID 37305870, 2023). "This is of potential interest since tenosynovial giant cell tumors (TGCTs) are characterized by rearrangements of CSF1, which is a ligand for CSF1R." (PMID 34888523, 2021). "In 2019, the FDA approved pexidartinib (Turalio), a small-molecule immunomodulator that targets the cytokine “colony stimulating factor-1(CSF-1)” receptor pathway, to treat symptomatic tenosynovial giant cell tumor." (PMID 33297561, 2020). "This study suggests that signaling between CSF1 and CSF1 receptor can be therapeutic target for tenosynovial giant-cell tumors." (PMID 30621224, 2019). "This approach was used before to detect the fusion transcripts KAT6A-CREBBP and CIC-DUX4 as well as a novel alternative transcript of CSF1 in an acute myeloid leukemia, a small round cell sarcoma, and tenosynovial giant cell tumors, respectively." (PMID 25621995, 2015). "On the other hand, patients with malignant tenosynovial giant cell tumors, defined by COL6A3::CSF1 fusion and low percentage neoplastic cells, are better diagnosed by target PCR instead of OGM." (PMID 40141463, 2025). "While clinical trials of small molecule CSF1R inhibitors and CSF1/CSF1R antibodies have been conducted in various types of cancer, a single reagent, PLX3397, has been clinically approved only for tenosynovial giant cell tumor (TGCT)." (PMID 39782686, 2025). "The CSF-1R inhibitor pexidartinib shrank tumor size and improved symptoms in patients with tenosynovial giant cell tumor (TGCT), with encouraging results in the phase III clinical study (NCT02371369) of CSF1/CSF1R-targeted therapy for benign diffuse TGCT." (PMID 39065562, 2024). "Tenosynovial giant cell tumor (TGCT) is a rare, locally aggressive neoplasm mainly characterized by colony-stimulating factor-1 (CSF1) translocations and CSF1 receptor (CSF1R) overexpression." (PMID 36209184, 2022). "Tenosynovial giant cell tumors (TGCT), are rare colony stimulating factor-1(CSF-1)-driven proliferative disorders affecting joints." (PMID 31601938, 2019).
viral infection (23 papers, 2008 to 2025). "Overall, these data suggest that PLX5622 is protective during lethal viral infection and that a CSF-1-independent mechanism of microglial proliferation during CSF1-R blockade becomes more conspicuous in WNE." (PMID 35401512, 2022). "Overall, these data suggest that IL-34 induces differential transcription programs and functions compared to CSF-1 during viral infection in high vertebrates and that IL-34 is able to display antagonist roles during viral infection." (PMID 33408768, 2021). "CSF-1 regulates the morphology and functions of mononuclear phagocytes and is necessary for immunity against intracellular fungal, bacterial, and viral infections in mice reviewed in." (PMID 24313934, 2013). "Rhesus macaques orally challenged with ΔrhBARF1 had decreased viral load indicating that CSF-1 is important for acute virus infection." (PMID 23300447, 2012). "CSF1 is one of the host gene targets most upregulated following viral infection." (PMID 33194826, 2020). "In fact, increased release of CSF1 may represent a predisposing factor for MAS and cytokine storm secondary to viral infection." (PMID 33194826, 2020). "Oral inoculation of rhesus macaques showed that the virus' ability to block CSF-1 was important for achieving the normally high viral loads during acute infection, and surprisingly, was also needed to establish normal levels of virus infection, or viral setpoint, during persistent infection." (PMID 23300447, 2012). "Additionally, the CSF1 signal, also originating from dendritic cells, was received by macrophages and dendritic cells via CSF3R and CSF1R, playing a role in differentiation and activation following viral infection." (PMID 38743760, 2024).
pulmonary fibrosis (22 papers, 2012 to 2025). Chronic progressive interstitial lung disorder characterized by the replacement of the lung tissue by connective tissue, leading to progressive dyspnea, respiratory failure, or right heart failure. "Neutrophils also strongly expressed Csf1 (encoding for macrophage colony-stimulating factor 1 (M-CSF)) that was recently shown to be required for the maintenance of MoAM in pulmonary fibrosis models." (PMID 38348034, 2024). "Our study provides insight into understanding a critical role for CSF1-induced AKT activation in the predisposition to lung fibrosis." (PMID 31750010, 2019). "This prediction is based on our previous data that showed CSF1 is important in IPF, and we surmise that this report clarifies a potential mechanism for this effect as a priming induced by CSF1 to predispose lung fibrosis in humans." (PMID 31750010, 2019). "As an essential factor for macrophage differentiation and proliferation, the inhibition of CSF-1/CSF-1R pathway affects macrophage production and thus attenuates lung fibrosis." (PMID 40007537, 2025). "The inhibition of the CSF-1/CSF-1R signaling pathway offers a novel therapeutic modality for mitigating radiation-induced pulmonary fibrosis." (PMID 40007537, 2025). "In mouse model of bleomycin-induced pulmonary fibrosis, knocking out CSF-1 or usage of CSF-1R inhibitor showed protective effect." (PMID 40007537, 2025). "Herein, we provide a comprehensive review of the CSF-1/CSF-1R signaling pathway in radiotherapy, with a focus on advances in macrophage-targeted strategies in the treatment of cancer and pulmonary fibrosis." (PMID 40007537, 2025). "Studies have shown that the CSF1 gene is among the genes that play an executive role in bleomycin-induced lung fibrosis." (PMID 39205185, 2024). "We previously reported that CSF1 plays an important role in pulmonary fibrosis in both mice and IPF patients." (PMID 31750010, 2019). "Intriguingly, pharmacologic inhibition of colony stimulating factor-1 (CSF-1) inhibited macrophage influx and attenuated RT-induced lung fibrosis in mice supporting a pathologic relevance of macrophages in RT-induced lung fibrosis." (PMID 31024543, 2019). "Previous data generated from our laboratory revealed that CSF1 contributes to pulmonary fibrosis in mice as CSF1−/−mice showed less fibrosis in response to bleomycin challenge." (PMID 31750010, 2019). "Therefore, exploring the physiological and pathological roles of CSF-1/CSF-1R signal transduction in tumor treatment and radiation-induced pulmonary fibrosis is of great significance for the comprehensive treatment of malignant tumors." (PMID 40007537, 2025). "The evidence of CSF-1/CSF-1R signaling pathway in radiation-induced pulmonary fibrosis is limited." (PMID 40007537, 2025). "In addition, studies showed that CSF-1 was elevated in alveolar lavage in patients with pulmonary fibrosis and stimulated macrophages and fibroblasts to participate in fibrosis formation." (PMID 40007537, 2025). "Previous data indicated that CSF-1 contributes to pulmonary fibrosis in mice." (PMID 40007537, 2025). "Blocking the CSF-1/CSF-1R signaling pathway may be a potential therapeutic target for pulmonary fibrosis." (PMID 40007537, 2025). "In a mouse model of asbestos-induced pulmonary fibrosis, CSF-1 monoclonal antibodies or inhibitor PLX3397 were used to block the CSF-1/CSF-1R signaling pathway to reduce monocyte differentiated alveolar macrophages and the alleviated pulmonary fibrosis was observed." (PMID 40007537, 2025). "In addition, cumulative evidence demonstrated that M2 phenotype macrophage is dominant in tissue fibrosis and the inhibition of CSF-1/CSF-1R signaling pathway ameliorated pulmonary fibrosis, including radiation-induced lung fibrosis." (PMID 40007537, 2025). "We and others reported that M-CSF/CSF-1, M-CSF-R and downstream AKT activation plays an important role in lung fibrosis in mice models and in IPF patients." (PMID 31750010, 2019).
pulmonary fibrosis (continued). "Other significant canonical pathways shared by both cell lines included the tumor microenvironment pathway and pulmonary fibrosis idiopathic signaling pathway, which were predicted to be inhibited in the MC38 CSF1 knockout cell line (z-scores = − 1.9 and − 3.2, respectively)." (PMID 37505292, 2023). "However, that report lacked critical mechanistic data about how CSF1 and M-CSF-R-mediated signaling contributes to lung fibrosis." (PMID 31750010, 2019).
colitis (20 papers, 2013 to 2024). Inflammation of the colon. "In a mouse model of colitis, the severity of colitis was made worse by the adoptive transfer of macrophages from vagotomized mice into macrophage colony-stimulating factor 1 (MCSF 1)-deficient animals, indicating the crucial function of macrophages in the vagal anti-inflammatory effect." (PMID 36233558, 2022). "Specifically, CSF-1-deficient mice and male CSF-1R+/- mice were reported to be less susceptible to dextran sulfate sodium (DSS)-induced colitis, and treatment with a CSF-1 neutralizing antibody or a CSF-1R blocking antibody was highly efficacious in this same model." (PMID 31710624, 2019). "As pre-treatment of mice with neutralizing anti-CSF-1 antibodies protects them from DSS-induced colitis, we investigated whether loss of CSF-1R expression also afforded protection." (PMID 23451116, 2013). "Further studies have indicated that treatment with an anti-CSF1 antibody significantly attenuates dextran sodium sulfate-induced colitis, thus highlighting the involvement of CSF1 in mucosal inflammation." (PMID 39113700, 2024). "Efficacy of JNJ-40346527 in TCT colitis was consistent with previous investigations of the role of CSF-1/CSF-1R in a second IBD model." (PMID 31710624, 2019). "Both the CSF-1 and the TNFα gene sets were enriched in the colonic mucosal transcriptomes of Crohn’s disease and in mouse colitis, and expression of both gene sets was highest in patients who did not respond to anti-TNFα therapy." (PMID 31710624, 2019). "Inhibition of CSF-1 suppressed DSS-induced colitis due to diminished immune cell infiltration of T cells and macrophages in colon tissue and reduction of TNFα, IL-1β and IL-6 levels." (PMID 29261815, 2017). "A role for CSF-1 in GI inflammatory responses has been shown by the demonstration that administration of an anti-CSF-1 neutralizing antibody in mice is partially protective in DSS-induced colitis." (PMID 23451116, 2013). "Moreover, two new essential factors were identified in reactive glia in POI, Csf1 and Csf3, with Csf1 recently implicated in EGC responses in a murine colitis model and human Crohn’s Disease28." (PMID 35962064, 2022). "It has also been shown to significantly decrease the expression of cyclooxygenase-2 (COX-2) and colony-stimulating factor-1, which could reduce the severity of colitis." (PMID 33868436, 2021). "Both IL34 (only trended) and CSF1 were increased in mouse DSS-induced colitis." (PMID 31552020, 2019). "However, similar to CD, expression of the CSF-1 gene set was further enriched in mice with TCT-colitis, and good concordance at the individual gene level existed between Crohn’s disease and the murine model." (PMID 31710624, 2019). "CSF-1 biology is activated in Crohn’s disease and in murine T cell transfer colitis." (PMID 31710624, 2019). "While PCs are not normally found in colon, because we observed decreased proliferation and altered cell fates of SI epithelial cells in CSF-1 - and CSF-1R -deficient mice, we decided to examine the effects of CSF-1 and CSF-1R deficiency in normal colon and in mice with DSS-induced colitis." (PMID 23451116, 2013). "However, in DSS colitis or TNFΔARE ileitis, the blockade of CSF1 and IL34 is most beneficial." (PMID 31552020, 2019). "Application of the CSF-1 and TNFα gene sets to the TCT colitis expression data revealed both differences as well as similarities in the mechanistic impact of JNJ-40346527 and anti-TNFα." (PMID 31710624, 2019). "In TCT colitis, the CSF-1R inhibitor, JNJ-40346527, effectively restored the CSF-1 and macrophage gene sets to baseline." (PMID 31710624, 2019). "In the light of the increased IL34 and CSF1 expression in the inflamed intestine of patients with IBD, we next assessed their involvement in the widely used DSS model of murine colitis." (PMID 25896238, 2015).
colitis (continued). "We examined transcriptional data from CD mucosa for evidence of CSF-1 pathway activation and tested JNJ-40346527 (PRV-6527), a small molecule inhibitor of CSF-1 receptor kinase (CSF-1R), for its ability to inhibit disease indices in murine colitis." (PMID 31710624, 2019). "GSVA indicated that the CSF-1 gene set was enriched in TCT colitis, only weakly and non-significantly impacted by anti-TNFα therapy, but robustly normalized following treatment with JNJ-40346527." (PMID 31710624, 2019). "Dual blockade of CSF1 and IL34 was slightly more efficacious at preventing disease in DSS colitis than the monotherapies, reducing the histology score compared to the control treatment but was less efficacious than the treatment with CSA, which reduced the histology score by >50%." (PMID 31552020, 2019). "In the present study, we demonstrate distinct expression patterns of IL34 and CSF1 in human normal intestine, regulation of IL34 and CSF1 with inflammation in human IBD and a mouse model of colitis, and identify intestinal epithelial cells as a cellular source of IL-34." (PMID 25896238, 2015). "In the present paper, we investigated the expression of IL34, CSF1 and their shared receptor CSF1R in normal human ileum and colon, in inflamed and non-inflamed tissues of CD and UC patients, and in a mouse model of experimental colitis." (PMID 25896238, 2015). "Soy oligosaccharides have been previously reported to inhibit colitis in a mouse model, as well as to suppress the expression of inflammatory biomarkers, including COX-2, CSF-1, and IL-6, without affecting the NF-κB expression level." (PMID 32708415, 2020).
periodontitis (20 papers, 2013 to 2025). An acute or chronic inflammatory process that affects the tissues that surround and support the teeth. "In conclusion, this study found that age, smoking, periodontitis, manifest caries, and the presence of tumors are associated with the salivary levels of CSF-1." (PMID 28779164, 2017). "Salivary levels of CSF-1 are associated with age, smoking, periodontitis, manifest caries, and the presence of muscle and joint diseases and tumors." (PMID 28779164, 2017). "CSF1 rs1058885 is associated with aggressive periodontitis in the Japanese population." (PMID 31554150, 2019). "Moreover, CSF1 gene expression is associated with aggressive periodontitis." (PMID 24339952, 2013). "IL-34 and CSF-1 levels are altered in several chronic inflammatory diseases, including periodontitis, rheumatoid arthritis and inflammatory bowel disease, making them interesting candidates as potential therapeutic targets or biomarkers of disease." (PMID 40389754, 2025). "It has been suggested that genetic variants of CSF1 and CSF1R are associated with different inflammatory diseases, such as asthma and periodontitis." (PMID 31554150, 2019). "With that in mind, this study aimed to evaluate the possible influence of age, sex, smoking, periodontitis, caries, and systemic conditions on salivary levels of CSF-1, as well as to assess a normal reference range for CSF-1 in saliva." (PMID 28779164, 2017). "We also reported that the significant differences in CSF-1 levels were lost for smoking, periodontitis, caries, and muscle and joint diseases when correcting for total amount of protein." (PMID 28779164, 2017). "This study evaluated the possible influence of age, sex, smoking, periodontitis, caries, and several systemic conditions on salivary levels of CSF-1." (PMID 28779164, 2017). "We recently identified the presence of CSF-1 in saliva as a potential biomarker candidate of periodontal disease with increased levels in periodontitis compared to healthy subjects, and correlations to clinical parameters of periodontal disease severity." (PMID 28779164, 2017). "We found that age, smoking, periodontitis, caries, and the presence of muscle and joint diseases are related to altered salivary levels of CSF-1." (PMID 28779164, 2017). "Comparing the Average global expression profile of neutrophils from healthy PDL versus neutrophils from PDL with periodontitis revealed increased expression of genes such as Il1b, Il1rn, Cebpb, Colec12, Ptgs2, Zfp36, Egr1, Atf3, Csf1, and Lars2 in periodontitis." (PMID 39588378, 2024). "Individuals having periodontitis and manifest caries had significantly higher levels of CSF-1." (PMID 28779164, 2017). "Participants without periodontitis (n = 74) exhibited mean (±SD) CSF-1 levels of 802.1 (±532.9) pg/ml, while participants with periodontitis (n = 220) showed mean (±SD) levels of 973.3 (±725.2) pg/ml." (PMID 28779164, 2017). "We reported significantly higher levels of CSF-1 in participants diagnosed with periodontitis, even when restricted to patients not having manifest caries." (PMID 28779164, 2017). "Interestingly, results showed an up-regulation of colony-stimulating factor-1 (CSF-1), S100A8/A9, S100A12, interleukin (IL)-1β, matrix metalloproteinase (MMP)-8, and hepatocyte growth factor (HGF), in patients with periodontitis with a statistical significance of p<0.001." (PMID 37224160, 2023). "Salivary CSF-1 levels were significantly increased in periodontitis compared to without." (PMID 28779164, 2017). "However, when we restricted the analysis to participants not having periodontitis, there was only a trend towards higher CSF-1 levels in subjects with manifest caries (p-value = 0.092), which suggest that the effects of caries on CSF-1 levels might partially be due to their periodontal condition." (PMID 28779164, 2017).